TUG1 (taurine up-regulated 1)
Diseases named in the same sentence as TUG1 in open-access papers (continued):
Sharing a sentence is not in itself a finding about the gene and the disease.
tumor (continued). "Using the NSCLC PDX models, the authors investigated the anti-tumour efficacy of silencing of TUG1 and LCAL6 lncRNAs using siRNAs." (PMID 36230680, 2022). "Many reports have demonstrated that TUG1 knockdown inhibits cancer progression and suppresses tumor growth in many cancers, including HCC." (PMID 35237695, 2022). "TUG1 promoted tumor progression and metastasis via modulating miR-140-3p and Annexin A8 axis in bladder cancer cells." (PMID 35928868, 2022). "For instance, upregulation of TUG1 facilitates tumor growth in laryngocarcinoma through targeting miR-145-5p/ROCK1 axis." (PMID 35601153, 2022). "In these malignant tumours, knockout of TUG1 can inhibit tumour cell proliferation, migration and clone formation." (PMID 35421276, 2022). "In CRC, miR-542-3p can impede tumor promotion via TUG1, and inhibit the proliferation, migration, and invasion through OTUB1, cortactin, or PI3K/AKT signaling." (PMID 35427373, 2022). "Previous investigations reported that lncRNA TUG1 showed tumor-suppressive or oncogenic functions in different types of cancers." (PMID 36333703, 2022). "Silencing of TUG1 suppressed tumor growth and lung metastasis and therefore increased survival of xenograft model mice." (PMID 35193488, 2022). "Lastly, we performed xenograft tumor in nude mice to evaluate the effect of SP1 on the tumorigenesis of CRC cells in vivo through regulation of the TUG1/miR-421/KDM2A/ERK pathway." (PMID 35508523, 2022). "TUG1 functions as a tumor suppressor in human glioma through promoting apoptosis and inhibiting cell proliferation." (PMID 34976181, 2022). "Numerous studies show that TUG1 controls drug resistance, cell differentiation, invasion, metastasis, apoptosis, tumor growth, and cell metabolism in various types of cancer." (PMID 37303492, 2022). "Because many studies have indicated that TUG1 inhibits tumor cell proliferation in HCC, we used a CCK-8 assay to screen the performance of the 15 siRNAs 72 h after transfecting them into wild-type HUH7 and Hep3B cells." (PMID 35237695, 2022). "Experimental studies have disclosed that TUG1 significantly stimulated tumor cell proliferation, invasion, colony formation, and drug resistance in CRC cells." (PMID 36333703, 2022). "Several ncRNAs, such as miR-491-3p, miR-613,and SUSD2 have been found to act as tumor suppressor genes in RB, but other ncRNAs, such as circ-E2F3, NEAT1, and TUG1 act as tumor promoter genes." (PMID 36619866, 2022). "Additional investigations on TUG1 have also highlighted its ability to mediate the apoptosis of lens epithelial cells by negatively-regulating miR-421, a tumor-suppressive miR in CRC." (PMID 35508523, 2022). "In cancer, TUG1 acts in a tissue- or context-specific manner either as tumor-suppressor or oncogene by affecting cancer cell proliferation, migration and invasion." (PMID 36173935, 2022). "TUG1 exerts its tumor-promotive function via diverse mechanisms including RNA-RNA interactions and the Wnt/β-catenin pathway." (PMID 35508523, 2022). "Studies revealed that TUG1 expression was increased in CRC tumor tissues and promoted cell proliferation." (PMID 36333703, 2022). "TUG1 knockdown induced by siRNA not only reduces immunosuppression but also suppresses tumor progression both in vitro and in vivo." (PMID 35237695, 2022). "TUG1 or TRIB2 loss of function prohibited proliferation, migration, invasion along with in vivo tumor growth but facilitated CRC apoptosis." (PMID 36333703, 2022). "For instance, for MALAT1, NEAT1, and TUG1, both oncogenic and tumor suppressor effects have been reported." (PMID 34322395, 2021).
tumor (continued). "TUNEL assay further demonstrated that the interference with lncRNA TUG1 and oxaliplatin treatment both facilitated the apoptosis in tumor tissues, and this facilitation was more remarkable in the Lv-shTUG1+OXA group." (PMID 34858502, 2021). "The lncRNA taurine upregulated gene 1 (TUG1) has been reported to exert oncogenic or tumor suppressive function in cancer through altering cancer-related gene expression at the transcriptional level." (PMID 33747256, 2021). "The pooled OR was 2.82 (95% CI: 1.84-4.33, p < 0.001) with significant heterogeneity (I2 = 72.2%, p < 0.001), demonstrating that patients with up-regulated TUG1 expression are more likely to develop higher tumor stage." (PMID 33747256, 2021). "For examples, inhibition of lncRNA TUG1 elevates miR-9-5p expression and attenuates the growth of OS tumor xenografts." (PMID 34141611, 2021). "The aberrantly expressed lncRNA TUG1 interferes with the proliferation, migration and invasion of tumor cells through various molecular mechanisms to promote or inhibit tumor development." (PMID 34793263, 2021). "TUG1 is a newly found cancer-related lncRNA, which is abnormally expressed in various types of cancers, and functions as an oncogene or tumor suppressor gene." (PMID 34659578, 2021). "A significant connection was found between high TUG1 expression and low tumor differentiation in cancer patients, and the pooled OR was 1.99 (95% CI: 1.10-3.60, p = 0.023) with statistical heterogeneity (I2 = 80.7%, p < 0.001)." (PMID 33747256, 2021). "LncRNA taurine upregulated gene 1 (TUG1) is essential for retinal development in the developing mouse eyes, and its abnormal expression is detected in tumorigenesis, either as a potential tumor suppressor or oncogene." (PMID 34429073, 2021). "Except for that, we have also illustrated that the knockdown of TUG1 and elevation of miR-187-3p were able to suppress tumor growth of PA in vivo." (PMID 34021124, 2021). "Over recent years, TUG1 overexpression has also been described in OS cells and tissues regarding adjacent non-tumor tissue and normal osteoblast cells." (PMID 33920083, 2021). "It was observed that mice accepted the injection of cell suspension treated with TUG1 silencing or miR-187-3p elevation had repressed tumor weight and volume, and miR-187-3p inhibition abrogated the impact of TUG1 repression." (PMID 34021124, 2021). "TUG1 expression in tumor tissues was evaluated by qRT-PCR, and the results showed that TUG1 level was lower in tumor tissues of the sh-TUG1-1 group than that of sh-NC group (p < 0.01)." (PMID 34362467, 2021). "Critically, a recent study authenticates that lncRNA ZnF503-AS1 recruits transcription factor GATA6 and thus exerts its tumor-suppressive function and lncRNA TUG1 enhances cell growth and apoptosis by epigenetically silencing of transcription factor KLF2." (PMID 34858502, 2021). "Among the lncRNAs involved in the model, several of them were reported to be associated with tumor progression, such as lncRNA TINCR and TUG1." (PMID 34873403, 2021). "TUG1 served as a tumor promoter, impeded the progression of CRC by miR-542-3p/TRIB2 axis to inactivate of Wnt/β-catenin pathway, which providing a novel target for CRC treatment." (PMID 34030715, 2021). "In these cancers, TUG1 plays oncogenic roles via enhancing the proliferative, migratory capacity of tumor cells." (PMID 34097717, 2021). "In most malignancies, TUG1 has been reported to be overexpressed and be involved in regulating of multiple processes in tumor progression, invasion and angiogenesis." (PMID 33747256, 2021). "To investigate the effects of TUG1 and miR-29a in vivo, we subcutaneously injected TUG1 knockdown cells, miR-29a knockout cells, or control cells into nude mice, and evaluated the tumor growth." (PMID 34659578, 2021). "In respiratory tumors, 4 NSCLC studies indicated that patients with upregulated TUG1 levels have better prognosis (HR = 0.46, 95% CI: 0.27-0.80, p = 0.061), which was opposite to other tumor types." (PMID 33747256, 2021).
tumor (continued). "A xenograft tumor model in nude mice was established to investigate the biological role of TUG1 in CRC in vivo." (PMID 34030715, 2021). "TUG1 promotes tumor-induced endothelial cell proliferation, migration and tube formation and enhances spheroid-based angiogenesis." (PMID 33634032, 2020). "After 5 weeks following the cell inoculation, tumor volume and weight were greatly inhibited in sh-TUG1 group compared with those in sh-NC group." (PMID 32390763, 2020). "Our study also found that lnc-TUG1 was significantly correlated with quiescent NK cells, suggesting that lnc-TUG1 had the potential to become a tumor immunotherapy target." (PMID 33194692, 2020). "Further investigations revealed that TUG1 can directly target miR-29c, a well-known tumor suppressor miRNA in cancers." (PMID 32042268, 2020). "By directly inhibiting miR-299, the lncRNA taurine upregulated 1 (TUG1) heightens tumor-induced angiogenesis." (PMID 32178454, 2020). "We observed a decrease in tumor growth in the sh-TUG1 group compared with the sh-NC group by the size and weight of the tumor." (PMID 31920462, 2020). "More importantly, TUG1 knockdown inhibited HCC tumor growth in vivo through upregulating miR-216b-5p via inactivation of the DLX2." (PMID 31920462, 2020). "Taurine upregulated 1 (TUG1) is upregulated in PC samples, and TUG1 knockdown exerts a significant tumor suppressor effect on PC behaviors." (PMID 32042268, 2020). "LncRNA TUG1 can also promote tumor angiogenesis; however, its mechanism is different in different tumor cells." (PMID 32993787, 2020). "In vivo, U87 and U251 xenograft models also showed ablation of TUG1 diminished the tumor microvessel density." (PMID 32178454, 2020). "The downregulation of TUG1 expression was connected with the inhibition of tumour growth and invasion in PAAD." (PMID 32550827, 2020). "TUG1 is a well-known EZH2-interacting lncRNA that regulates the oncogenic pathway to promote tumor progression." (PMID 31973032, 2020). "Noticeably, high expression of TUG1 in CRC had a significant correlation with the depth of tumor and AJCC stage." (PMID 31528224, 2019). "TUG1 was significantly up-regulated in tumor tissues resected from the case with recurrent CRC patients and low in the case without recurrence." (PMID 31528224, 2019). "The asTUG1/uPIC potently suppressed tumour growth compared with the asLuc/uPIC control, consistent with the TUG1 silencing results." (PMID 31019193, 2019). "For instance, TUG1 has been reported as a tumor suppressor in human glioma, while it highlighted a potential oncogenic role in osteosarcoma." (PMID 31532756, 2019). "LncRNA taurine-upregulated gene 1 (TUG1), originally identified as a transcript up-regulated by taurine, is expressed in a tissue specific pattern and acts as either an oncogene or a tumor suppressor in human cancers." (PMID 31532756, 2019). "The lncRNA TUG1 (taurine upregulated gene 1) is differently expressed in different tissues and performs oncogenic or tumor suppressor functions in different cancers." (PMID 31212809, 2019). "As a tumour promoter in OS progression, TUG1 was significantly overexpressed in tumour tissues and cell lines." (PMID 30911001, 2019). "In Dong’s research group study, they demonstrated that TUG1 promotes tumour angiogenesis via up-regulating the expression level of VEGFA by sponging miR-34a." (PMID 34968230, 2019). "Clinically, elevated TUG1 levels in OS patients significantly correlated with tumour size, distant metastasis, TNM stage, and overall and recurrence-free survival." (PMID 30911001, 2019). "Smaller size of tumor xenografts of DDP resistant NSCLC cells in the presence of TUG1 demonstrated enhancement of chemosensitivity by TUG1 in vivo." (PMID 31532756, 2019). "Statistical analysis suggested that TUG1 expression was significantly related to tumour size, distant metastasis, and TNM stage." (PMID 30911001, 2019).
tumor (continued). "Here we report, for the first time, that TUG1 promotes tumor cell migration, invasion, and proliferation in PCa by working in key aspects of biological behaviors." (PMID 29967294, 2018). "A lower expression of TUG1 was associated with a higher TNM stage and tumour size, as well as poorer overall survival for patients with NSCLC." (PMID 30595764, 2018). "Western blot analysis revealed that TUG1 knockdown or DDP exposure pointedly increased PDCD4 protein level in tumor tissues." (PMID 30519392, 2018). "To confirm the result, we further investigated TUG1 expression in ESCC tumor tissues and adjacent normal tissues by qRT-PCR analysis." (PMID 30519392, 2018). "TUG1 is extensively related to human malignancies, reported having either tumor promoting or tumor suppressing functions in different types of cancers." (PMID 30116729, 2018). "Our data showed an opposite deregulation trend in CRC tissues and in serum exosomes for TUG1, which is downregulated within tumor cells and upregulated in serum exosomes." (PMID 30195762, 2018). "The downregulation of miR-29c abolished the TUG1 knockdown-mediated inhibition of tumour growth in vitro and in vivo, whereas the upregulation of miR-29c enhanced the effects of TUG1 knockdown on PC cells." (PMID 30595764, 2018). "Recently, TUG1 was considered to be abnormally regulated during tumorigenesis as a potential tumor suppressor or as an oncogene." (PMID 29674645, 2018). "Overexpression of miR-299 significantly suppressed spheroid-based tumor-induced formation of blood vessels in vitro and tumor growth in vivo, while knockdown of TUG1 decreased the expression level of VEGFA, a molecular switch of tumor angiogenesis." (PMID 30217088, 2018). "The data revealed that TUG1 knockdown or DDP treatment significantly suppressed tumor growth, evidenced by the diminished tumor volume and tumor weight." (PMID 30519392, 2018). "TUG1 was again highly expressed in a subset of tumours (n = 166, 40.7%), but 59.3% of tumour samples (n = 242) displayed low TUG1 expression." (PMID 28430799, 2017). "qRT-PCR analysis of TUG1 expression found it to be significantly lower in tumor tissues formed from shTUG1 group than those from controls." (PMID 28069000, 2017). "A significant connection was found between a high TUG1 expression level and high tumor stage in cancer patients (pooled OR= 3.45, 95% CI: 2.19-5.44, P<0.00001)." (PMID 28977959, 2017). "Univariate analysis revealed that tumor stage, intrahepatic metastasis, venous invasion, perineural invasion, and TUG1 expression were all significantly correlated with OS and DFS." (PMID 29371936, 2017). "Radiation treatment dramatically reduced the tumor volume and weight in xenograft model, and this effect was more obvious when combined with TUG1 silencing." (PMID 28376901, 2017). "On the contrary, tumours with significantly increased TUG1 expression, which encompass 8% of TCGA cases, were usually positive for markers of a luminal subtype, e.g. FOXA1, GATA3, but not for basal KRTs." (PMID 28430799, 2017). "Although the tumor-promoting capacity of TUG1 has been well documented in other cancers, its potential contribution to ICC pathogenicity remains undefined." (PMID 29371936, 2017). "To detect the clinical significance of TUG1 expression in tumor patients, we carried out current systematic review and meta-analysis investigating its relation with the prognosis and clinicopathological features of cancers." (PMID 29029461, 2017). "Four weeks later, the mean tumor volume for the TUG1-knockdown group and the drugs group was obviously smaller than that of the control group." (PMID 28069000, 2017). "Knockdown of TUG1 increases blood-tumor barrier (BTB) permeability via binding to miR-144 and reducing tight junction protein expression in endothelial cells through targeting HSF2." (PMID 28717243, 2017).
tumor (continued). "Knockdown of TUG1 exerts tumor‐suppressive functions by reducing cell proliferation and inducing cell apoptosis via the caspase signaling pathway." (PMID 28088836, 2017). "TUG1 was overexpressed in ICC compared to corresponding non-tumor tissues (3.68 ± 0.2 vs 1.54 ± 0.1, P < 0.001)." (PMID 29371936, 2017). "In our in vivo experiments, changes in tumor volume and growth rate in response to TUG1 silencing further verified its regulatory effect on the growth of HCC cells." (PMID 29029483, 2017). "The median ratio of relative TUG1 expression (3.78) in tumor tissues was used to divide the samples into two groups." (PMID 29371936, 2017). "Eight hundred twenty-six patients in nine eligible studies were included to detect the relationship between the TUG1 expression levels and tumor stage in this meta-analysis." (PMID 28977959, 2017). "The results demonstrated that radiation treatment significantly inhibited the tumor growth, including the average volume and weight, and this effect was more evident when combined with TUG1 knockdown." (PMID 28376901, 2017). "As a result, the patients with lager tumor size were significantly increased in the high TUG1 expression group." (PMID 28977959, 2017). "The heterogeneity was probably due to the differences in the cancer type, the clinical characteristics of patients (country, age, tumor stage, etc.), the cut off value of lncRNA TUG1, the sample size, the time of follow-up, and so on." (PMID 28548946, 2017). "Taken together, these results indicated that TUG1 downregulated miR-132 expression to inhibit tumor growth of HCC by modulating Hh signaling in vitro and in vivo." (PMID 29029483, 2017). "For instance, TUG1 expression was remarkably increased in high-grade MIBC tumor tissues, and TUG1 silencing suppressed proliferation and migration in high-grade MIBC." (PMID 28376901, 2017). "As in set 1, in the extended TCGA dataset more cases with low TUG1 expression were found among the muscle-invasive tumours." (PMID 28430799, 2017). "Subsequently, we set out to throw light upon the prognostic role of lncRNA TUG1 with lymph node metastasis and tumor progression in various cancers." (PMID 28548946, 2017). "TUG1 expression was also related to distant metastasis (OR=3.24, 95% CI: 1.18-8.93), large tumor size (OR=4.07, 95% CI: 1.08-15.28) and advanced tumor stage (OR=3.45, 95% CI: 2.19-5.44)." (PMID 28977959, 2017). "TUG1 expression level was significantly higher in SCLC tumor tissues than those in normal counterparts (P < 0.01)." (PMID 28069000, 2017). "We included expression analysis of TUG1 in 796 tumor samples’ and 105 normal breast tissue samples’ RNA-seq datasets from TCGA." (PMID 29657297, 2017). "Further analysis revealed that tumours with low TUG1 expression are characterized by a basal-squamous-like subtype signature accounting for the association with poor outcome." (PMID 28430799, 2017). "In multiple cancers, high levels of TUG1 expression are significantly correlated with poor OS, DM, large tumor size and advanced tumor stage." (PMID 28977959, 2017). "Recent studies manifested that lncRNA TUG1 contribute to the tumor progression through its regulation of diverse cellular processes, including migration, invasion, proliferation, differentiation, and apoptosis." (PMID 28548946, 2017). "In our study, we investigated the TUG1 expression in tumor tissues and matched adjacent normal mucosa tissues from 88 patients with CRC, and a panel of CRC cell lines." (PMID 27421138, 2016). "By data statistics and analysis, we observed that TUG1 expression was significantly elevated in tumor tissues compared with para-tumor tissue, and univariate analysis revealed a close association between high TUG1 expression and patient survival." (PMID 26856330, 2016). "Lower expression of Tug1 correlates with highertumor stage, increased tumor size and decreased overall survival." (PMID 27508057, 2016).